AGO2 (argonaute RISC catalytic component 2)
Diseases named in the same sentence as AGO2 in open-access papers (continued):
Sharing a sentence is not in itself a finding about the gene and the disease.
infection (continued). "Tolerance to infection with PVX does not appear to be attributed to the roles of DCL2, DCL4, and AGO2 in antiviral RNA silencing." (PMID 33032637, 2020). "First, the HC-Pro suppressor encoded by TuMV has no inhibitory effects on AGO1-dependent miR403-guided cleavage of AGO2 transcripts, confirming the absence of VSR activity in cells undergoing early stages of infection at the virus front." (PMID 33230160, 2020). "In Arabidopsis plants lacking DCL4, AGO2, RDR1 or RDR6, TuMV‐AS9‐GFP established local infection and moved systemically into non‐inoculated leaves, without reaching the inflorescence." (PMID 31286679, 2019). "Interestingly, Ago2, Ago3 and Piwi 6 silencing resulted in a significant decrease of DENV-1 replication during single infection, but this was not the case in the DENV+ZIKV co-infected cells." (PMID 37440582, 2023). "Our findings validate the role of Ago2 as a key player in the antiviral response in Ae. aegypti during Semliki Forest virus (SFV; Togaviridae, Alphavirus) and Bunyamwera orthobunyavirus (BUNV; Bunyavirales, Peribunyaviridae), but not ZIKV, infection." (PMID 34205194, 2021). "However, we detected a markedly enhanced accumulation of AGO1, AGO2, and PACT, but not Dicer or TRBP in the nucleus of 293T cells after infection with IAV-WSN compared to mock infection or infection with IAV-PR8 or Sendai virus (lane 2)." (PMID 33281788, 2020). "In the systemic leaves of RCY1‐HA plants with local CMV(Y) infection AGO2 was expressed also in the absence of challenge (CMV(Y)+, WS−; yellow column), but this response was lower than in the systemically challenged RCY1‐HA plants with local infection (CMV(Y)+, WS+; yellow column)." (PMID 33073913, 2021).
bacterial infection (6 papers, 2011 to 2023). "Moreover, the tsn1/tsn2 mutant was more resistant to bacterial infection, which is consistent with increased level of AGO2-associated sRNAs." (PMID 30783097, 2019). "Indeed, miR393*, which has a 5′A, associates with AGO2, and ago2 mutants are impaired in the regulation of genes involved in the response to bacterial infection." (PMID 22174881, 2011). "Among the ten AGOs in Arabidopsis, only AGO2 is induced by bacterial infection and is known to positively regulate immunity." (PMID 30783097, 2019). "AGO2 is a core component of the RNAi machinery and contributes to plant immunity during bacterial infection." (PMID 30783097, 2019). "Among the 10 Arabidopsis AGOs, only AGO2 is highly induced by bacterial infection and positively regulates antibacterial defense responses." (PMID 30783097, 2019). "Indeed, gibberellic acid, UV irradiation and bacterial infection upregulated AGO2 mRNA revealing that AGO2 was regulated by a variety of biotic and abiotic stresses." (PMID 33925878, 2021). "Conversely, among the ten AGOs in Arabidopsis, only AGO2 is induced by bacterial infection and AGO2 positively regulates immunity by protein arginine methyltransferase 5 (PRMT5)-mediated dual regulation of this protein as well as associated sRNA levels to ensure appropriate plant immune responses." (PMID 32764599, 2020). "To test whether the pAGO2:3HA:Δ59AGO2 plants, that accumulated higher levels of AGO2, are also more resistant to Pst infection as observed in prmt, we performed a bacterial infection assay and examined sRNA loading into AGO2." (PMID 30783097, 2019). "The pAGO2:3HA:Δ59AGO2 plants showed higher susceptibility to bacterial infection, similar to the ago2-1 mutant phenotype, further suggesting that the N-terminal GAR domain is important for AGO2 function in addition to its role in modulating AGO2 stability." (PMID 30783097, 2019). "The AGO2 protein’s role in enhancing the secretion of the PR1 protein, a marker of the SA signaling pathway, was revealed, which led to an increase in plant resistance to bacterial infection." (PMID 38138127, 2023). "Under normal growth conditions without bacterial infection, the AGO2-mediated RNAi pathway needs to be properly controlled to dampen plant immune responses." (PMID 30783097, 2019).
neurological diseases (4 papers, 2017 to 2023). "Our study provides new insights into Ago2 function and may represent a new therapeutic approach for ED and other vascular and neurological diseases." (PMID 36769259, 2023). "Interestingly, the silencing of ciRS-7 can occur through the recruitment of Argonaute 2 (Ago2) protein and the interaction between ciRS-7 and miR-651-5p, a ncRNA downregulated in PD patients with several targets in the brain related to neurological disease, included SNCA." (PMID 38249528, 2023).
neurodegenerative disease (3 papers, 2021 to 2022). A disorder of the central nervous system characterized by gradual and progressive loss of neural tissue and neurologic function. "Both SRP54 and AGO2 have previously been implicated in neurodegenerative diseases; however, no such connections have been made with PD before our findings." (PMID 34685771, 2021). "Thus, the lack of sufficient Ago2 in muscles and specifically at NMJs may impair the reparative actions of miRNAs in progressive neurodegenerative diseases such as ALS." (PMID 35301367, 2022).
kidney disease (2 papers, 2014 to 2021). "From comparisons of AGO2-IP RNAs, besides Fis1 encoding the mitochondrial fission protein FIS122–24, we also examined other candidate targets of miR-379 with putative functions related to kidney disease." (PMID 33398021, 2021).
hematologic malignancies (1 paper, 2025). "One of the key proteins implicated in this complex transport process is Argonaute2 (Ago2); however, mitochondrial miR-derived species and hematologic malignancies still remain unconnected." (PMID 41020880, 2025).
metabolic disease (1 paper, 2018). A congenital disorder (due to inherited enzyme abnormality) or acquired (due to failure of a metabolically important organ) disorder resulting from an abnormal metabolic process. "These Ago2-mediated molecular events may solve the paradox of protein biosynthesis in the obese liver, demonstrate a new mechanism in the regulation of basal metabolic activity, and provide a novel therapeutic target for metabolic diseases." (PMID 30201950, 2018).
vasculopathy (1 paper, 2023). "Therefore, we hypothesized that the decreased expression of Ago2 might be involved in the vasculopathy phenomena in diabetic ED." (PMID 36769259, 2023).
AGO2 also shares sentences with these, for which no sentence is quoted: multiple myeloma (5 papers); papillary thyroid carcinoma (4); amyotrophic lateral sclerosis (3); atherosclerosis (3); endometrial cancer (3); cardiovascular disease (2); Hyperglycemia (2); myocardial ischemia (2); acute lymphocytic leukemia (1); acute monocytic leukemia (1); acute myeloid leukemia (1); acute-on-chronic liver failure (1); adrenocortical carcinoma (1); age-related macular degeneration (1); allergic rhinitis (1); Anorexia (1); anti-phospholipid syndrome (1); Anxiety (1); aphthous ulcers (1); Ataxia (1); Ataxia with vitamin E deficiency (1); Atrophy (1); benign tumors (1); bone cancer (1); breast disease (1); Breast Invasive Lobular Carcinoma (1); cerebral malaria (1); chronic hepatitis B (1); chronic Hepatitis C (1); CNS DLBCL (1).
A further 53 diseases each share a sentence with AGO2 in 1 paper.